TNF (tumor necrosis factor)
Diseases named in the same sentence as TNF in open-access papers (continued):
Sharing a sentence is not in itself a finding about the gene and the disease.
infection (continued). "In addition, the evolved strain (Evo) showed transiently increased virulence in a systemic mouse infection model, which correlated with increased organ-specific fungal burden and inflammatory response (TNFα and IL-6) in the brain." (PMID 25356907, 2014). "These exciting results clearly indicate that the response of ‘arthritic’ osteoblasts to RRV infection differs from normal osteoblasts; they are more susceptible to infection possibly through delayed type I IFNs response and produce higher levels of IL-6, IL-1β, CCL2 and TNF-α." (PMID 25407789, 2014). "An increase in TNFα production followed by elevated PG secretion undoubtedly may have an important role in innate resistance of the endometrium to infection." (PMID 25028529, 2014). "As expected, TNF, IL-23, and IL-6 were produced during infection." (PMID 25309905, 2014). "The production of TNF-α, an important host mediator in the pathogenesis of septic shock, induced by either ΔspxA1 or ΔspxA2, is significantly lower than that induced by the WT strain at 6 h post-infection." (PMID 25264876, 2014). "Phil82 IAV induced robust TNF and IL-6 production after 18 hrs of infection as previously reported." (PMID 24988208, 2014). "In contrast, cytokines generally induced in the later stage of acute pathogenic infection, such as IL-6, IL-18 and TNF-α, were less or not increased, suggesting an early control of IA." (PMID 24991927, 2014). "During infection, secreted TNF-α due to BAG-mediated TLR9 activation as well as activation by other components of B. anthracis might enhance LT-mediated macrophage cytotoxicity and eventually increases the lethality of mice." (PMID 25472474, 2014). "Levels of CXCL1/KC, IFN-γ, TNF-α, and IL-10 in the lung 1, 7, 15 and 30 days post-infection were significantly higher (approximately 30%, 40%, 19% and 36%, respectively) (p<0.05) in mice infected with the L27/01 strain, particularly 1 to 7 days post-infection." (PMID 25392951, 2014). "Moreover, this coincided with a burst of the pro-inflammatory cytokines IL-1β and TNF-α in early and late stages of infection (day 8 p.i.)." (PMID 25075973, 2014). "Since TNF inhibitor therapy can increase the incidence of infections in RA, it is possible that increased infections observed in RA during TNF inhibitor therapy could be a cause of RA flares, which in turn could have an impact on RA disease activity." (PMID 25414636, 2014). "Given the safety profiles of SSRIs, their widespread use, and their ability to modulate TNF-α levels and induce autophagy during infection, they are attractive candidates for further exploring the possibility of tailoring TNF-α levels to optimize host response in the infected individual." (PMID 24586159, 2014). "Furthermore, TNFα treatment at the time of infection prevented LTR transcriptional silencing days later, as PMA/Iono treatment prior to analysis had no further effect in reducing the proportion of non-productively infected cells." (PMID 24502247, 2014). "However, despite p65 translocation, infection with vv811ΔA49 still prevented the TNF-α- and IL-1β-induced activity of an NF-κB reporter and inhibited the transcription and production of cytokines induced by these agonists." (PMID 24371075, 2014). "Normal expression levels of TNF-α and IL-6 in the blood of healthy individuals aid the prevention of infection and enhance immune function; however, overexpression may result in injury to tissues." (PMID 25371725, 2014). "Another pathogenesis component of some highly pathogenic H5N1 strains is a prolonged cytokine storm triggered upon infection, particularly tumor necrosis factor (TNF)-alpha and interferon (IFN) beta, which were found to be elevated in deadly cases compared to patients who survived the infection." (PMID 25436508, 2014).
infection (continued). "Conversely, it is likely that individuals that produce low levels of TNF-α upon infection with M. tuberculosis may benefit from adjunctive therapy that enhances production." (PMID 24586159, 2014). "It is likely that infection-induced production of inflammatory cytokines, such as TNF-α, IL-1, and IFN-γ, may stimulate CX3CR1 production in HAEC." (PMID 24851083, 2014). "Specifically, we tested whether miR-155 overexpression or inhibition prior to infection could alter the magnitude of F. tularensis-triggered TNFα or IL-6 secretion." (PMID 25295729, 2014). "To determine the consequences of EGFP-PrPC overexpression on rod formation per se or in the context of Aβd/t or TNFα, we infected rat hippocampal neurons at different multiplicity of infections (MOI) compared to control adenovirus expressing GFP at the highest MOI." (PMID 24760020, 2014). "BCG-TB1860His infection also resulted in similar reduction of IL-2, IL-6, IL-12p40 and TNF-α." (PMID 24945624, 2014). "Interestingly, expression level of TNF-α declined in lung while increased in brain at 6 dpi after infection." (PMID 25547136, 2014). "TNF-α is important in the procedure of granuloma formation and the infection localized." (PMID 25303675, 2014). "While similar levels of TNF-α and IL-6 were released after infection with low dose C. pneumoniae or stimulation with 1 ng/mL LPS, low dose C. pneumoniae induced higher levels of IL-1β, IL-12p40 and IL-12p70 over time than LPS, which was shown to be statistically significant." (PMID 25488836, 2014). "Thymic atrophy is also seen in other infections and results from the inflammatory syndrome mediated by TNF-α during the acute phase of infection; this leads to activation of the hypothalamus-pituitary-adrenal (HPA) axis with the consequent release of corticosterone." (PMID 25330249, 2014). "Moreover, pre-treatment with anti-TNF-α MAbs resulted in lower systemic cytokine levels and less end-organ tissue injury at 48 hours after infection." (PMID 24743949, 2014). "Furthermore, this infection actively stimulates an innate immune response which results in increases in expression of CXCL8 and TNF-α that have been implicated in ovine abortion following C. abortus infection." (PMID 25010668, 2014). "Results indicated that peak TNF- α and substantial IL-6 expression at 3 hours post infection." (PMID 25299049, 2014). "Infection of the uterus is accompanied by systemic fluctuations of inflammatory cytokines like tumor necrosis factor (TNF), interleukin (IL)-1, IL-6, and acute phase proteins (APP) such as lipopolysaccharide-binding protein (LBP), serum amyloid A (SAA), and haptoglobin (Hp)." (PMID 25919010, 2014). "We can speculate that for Cyp3a11 and 3a25, there could be two opposing signals due to infection, of which the suppressive effect of TNFα is dominant." (PMID 24707356, 2014). "In addition, infection with viable P. aeruginosa for 6 hours resulted in an infiltrate of TNF-α-expressing cells into lungs." (PMID 25034539, 2014). "The source of TNF mRNA expression in the cardiac tissue is unclear; however, both myocardial and heart infiltrating inflammatory cells may contribute to amplify local TNF production in chagasic infection." (PMID 25140115, 2014). "Notably, IFN-γ and TNF-α, two cytokines participating actively in parasite control during the early stage of the infection, peak around the first week post-infection." (PMID 24722489, 2014). "In the macrophage infection model, LsfA is required for P. aeruginosa resistance to clearance, with lower TNF-α production in macrophages infected with the PA14 strain compared with macrophages infected with lsfA mutants, suggesting that LsfA plays a role in the PA14 immunomodulatory effect." (PMID 25329795, 2014). "In addition, the balance between IFN-γ and TNF-α is the key mediators in triggering effector functions against T. gondii during both acute and chronic stages of infection." (PMID 25352834, 2014).
infection (continued). "Early induction of IL-1β and TNF-α by rBRSVΔSH in the lungs may have contributed to rapid control of virus replication and, therefore, less inflammation, 6 days after infection." (PMID 24700100, 2014). "On the other hand, TNFα mRNA increased 200-fold after infection with U112, and TNFα and IL-6 levels in the culture medium were up to 30-fold higher than we observed for LVS and Schu S4, confirming that F. novicida is significantly more proinflammatory than F. tularensis." (PMID 25295729, 2014). "Similarly to TNF, IL-1β is also an endogenous pyrogen that is produced and released at the early stages of the immune response to infections, lesions, and stress." (PMID 25339958, 2014). "Infection increased secretion of cytokines/mediators IL-1RA, IL-6, TNF-α and TIMP-1." (PMID 24416445, 2014). "Both of them significantly decreased the invasion and TNF-α expression induced by infection." (PMID 25133542, 2014). "However, the extrinsic pathway appeared not to participate in mast cell apoptosis as induced by IAV, as demonstrated by the feeble cleavage and activation of zymogen pro-caspase 8, although TNF-α was significantly induced during the infection." (PMID 24923273, 2014). "Besides, Serum levels of TNF-α and IL-6 in mice infected with mutant strains return to basal levels at 9 h post infection, more quickly than in WT-infected mice." (PMID 25264876, 2014). "Activated TLR signaling results in the production of various inflammatory molecules such as inducible nitric oxide synthase, cyclooxygenase-2, tumor necrosis factor (TNF)-α and interleukin (IL)-1β to control and eliminate the infection by leukocyte recruitment and inflammation." (PMID 25077631, 2014). "A variety of cell types can produce TNFα during the immune response to infection." (PMID 24854422, 2014). "TNF-α is a multifunctional cytokine that is significant for activation of macrophages and dendritic cells, granuloma formation and recruitment of lymphocytes to the infection foci during infection." (PMID 25208737, 2014). "A careful analysis of the systemic (serum) cytokine levels in mice chronically infected with the Omani isolate revealed that type 1 (IFN-γ, TNF-α, GM-CSF), type 2 (IL-5, IL-13, to a lesser degree IL-4), and type 17 (IL-17) cytokines coexisted throughout the infection." (PMID 25398130, 2014). "Also a strong upregulation of the proinflammatory genes COX-2, IL-1β, and TNFα was observed in a monocyte/macrophage cell line of trout (RTS11) in response to an infection with Achlya." (PMID 25088077, 2014). "We describe a new mechanism for HCV to use TNF-α to promote infection of polarized hepatocytes." (PMID 24259385, 2014). "This indicated that the TNF signal was activated upon SVCV infection." (PMID 25344771, 2014). "Six days following C. jejuni infection hepatic IFN-γ, TNF-α, and IL-6 concentrations increased (p < 0.05−0.0001), but to even higher levels upon ΔhtrA knockout mutant as compared to parental C. jejuni WT strain infection (p < 0.05)." (PMID 24959425, 2014). "FDA-approved phosphodiesterase (PDE) inhibitors, which alter intracellular levels of cAMP resulting in reduced TNF-α secretion, likewise have been shown to reduce bacterial burden in rabbit and mouse models of infection when combined with current antimycobacterial antibiotics." (PMID 24586159, 2014). "Our data demonstrate that LVS infection markedly impaired LPS-stimulated TNFα secretion in MDMs." (PMID 25295729, 2014). "We previously reported the lower production of TNF-α induced by infection with a MV strain of CSFV, and suggested that, in contrast to HV strains, TNF-α may be of secondary importance with MV strains." (PMID 23398967, 2013). "In alveolar epithelial cells infection of Moraxella catarrhalis was shown to induce monocyte adhesion, transepithelial migration and superoxidegeneration, whereas stimulation with lipopolysaccharide (LPS), TNFα, IL-1β or IFN-γ induced adhesion or TM." (PMID 23448224, 2013).
infection (continued). "In our birth cohort, infants with high levels of TNF-α and IL-1β at birth persist in this pattern during infancy, and these intrinsically higher levels might act early during an infection to control parasite density." (PMID 24130857, 2013). "After infection with some pathogens, systemic inflammation is usually induced via the active secretion (from immune cells) of proinflammatory cytokines, such as the tumor necrosis factor-α (TNF-α) and interferon-γ (IFN-γ), which can induce depressive symptoms." (PMID 23977312, 2013). "To test whether inflammation is required for GI tract bacteria-triggered prostate pathology, we performed systemic neutralization of TNF-α using intraperitoneal injection of anti-TNF-α antibody for 3 weeks duration starting at 3 weeks post-infection (PI)." (PMID 23991210, 2013). "The correlation coefficients (R2) for TNF-α, IL-1β, IL-6 and IL-12 with percent apoptosis were 0.906, 0.864, 0.879 and 0.890 respectively (P<0.05) on 5th day and 0.830, 0.669, 0.639 and 0.846 respectively (P<0.05) on 6th day of infection." (PMID 23667550, 2013). "Therefore, it became clear that besides mortality rates and organization of lesions, TNF-α also controlled the migration of inflammatory cells to the site of infection." (PMID 23936574, 2013). "We found that production of TNF-α and NO persisted 24 h after infection." (PMID 23533310, 2013). "This hypothesis is supported by the stronger DTH response, the decreased severity of infection, and the significantly lower amount of variation seen in TNF-α levels in the lungs of the modulated group." (PMID 23326551, 2013). "However, following JaOArS982 infection the levels of IFN-γ in TNF-α KO mice were significantly increased compared with those of WT mice at 5 and 9 days pi." (PMID 23940775, 2013). "TNF-α, another inflammatory cytokine and activator of neutrophils, was also significantly upregulated in colonic tissue from CD4cre+ mice early during infection." (PMID 23469071, 2013). "Moreover, DV2 infection resulted in elevated serum levels of the cytokines tumor necrosis factor-α and interlukin-6 and obvious histopathological changes in the liver." (PMID 23383181, 2013). "Both IFNα and IFNβ are recognized by a heterodimeric receptor composed of the two subunits IFNAR1 and IFNAR2, and in general promote an anti-inflammatory response during infection, for example by reducing the production of pro-inflammatory cytokines IL-1 and TNFα." (PMID 24244159, 2013). "Each combination of parameters yields ratios of average tissue concentrations ([TNF-α]/[IL-10]), which we plot against representative model outputs of total bacterial load, number of activated Mφs, and apoptosis of resting Mφs at 200 days post-infection." (PMID 23869227, 2013). "Therefore, we evaluate the levels of BAL and serum IL-6, IFN-β and TNF-α on day 2 post-infection and the concentrations of IFN-γ and IL-10 on day 5 after challenge." (PMID 23947615, 2013). "TNF-α expression served as a positive control that is expected to increase early with infection." (PMID 24339776, 2013). "However, under treatment with an anti-TNF-α drug, microorganisms survive easily, and the focal infection tends to persist with a mild inflammation." (PMID 23738990, 2013). "For example, a high level of TNF-α is a crucial factor for controlling primary infection, as it induces the expression of other proinflammatory cytokines such as IL-1 and of several chemotactic cytokines, which attract immune cells to the site of infection." (PMID 24349452, 2013). "TNFα production is also detected at the site of infection in TB patients." (PMID 24350246, 2013). "Many recalled that becoming ill with an infection meant they’d had to stop taking anti-TNF." (PMID 23663548, 2013). "However, by 2 days after infection the TNF-α level in Lum−/− infected corneas was significantly higher - 930 pg/ml versus 210 pg/ml, and by 5 days it was 1607 pg/ml in infected Lum−/− versus 963 pg/ml in wild type corneas." (PMID 23358433, 2013).
infection (continued). "Interestingly, TNF-α/IL-2 expressing central memory-like CD4 T cells showed a significant positive correlation with protection at week 6 post infection, whereas the opposite was observed for post infection CD4 T cells producing only IFN-γ." (PMID 23977248, 2013). "Only IL-1β, IL-6, TNF and IL-4 were significantly induced by infection in the spleen (the latter also in the liver), while the production of IL-12p70 and IL-13 decreased with infection, in the liver." (PMID 23459556, 2013). "However, uncontrolled IFN-γ-induced immune responses including TNF and NO production as the infection persists induce tissue pathogenicity and death of the host." (PMID 24204274, 2013). "Transcripts of TNF-α are found in the infected GT tissues as early as day 3 after infection." (PMID 23483844, 2013). "In this study we showed that the agsΔ mutants displayed a reduced virulence associated with an inhibition of germination in vivo and a reduction of the inflammatory response after 24 h infection (decreased TNFα and increased IL10 expressions and reduced recruitment of PMNs)." (PMID 24244155, 2013). "Moreover, blood TNF-α was also abundantly produced in the TLR2-deficient mice and peaked to levels 2.3-fold higher than those in WT mice at 6 h post-infection." (PMID 24058538, 2013). "In addition, inflammatory cytokines such as IL-1β, IL-6, and TNF-α activate coagulation systems in infection, trauma, inflammation, and cancer." (PMID 23874602, 2013). "Further, although TNF is essential for the early control of infection by either virulent or attenuated mycobacteria, IL-1 pathway is dispensable for controlling less virulent infection by M. bovis BCG." (PMID 25400917, 2013). "Tumor necrosis factor (TNF-α) and interleukin-6 (IL-6) are pro-inflammatory cytokines, and while TNF-α activates innate responses to infection and promotes an anti-viral state in cells, IL-6 has been described as one of the mediator coordinating the interface between adaptive and innate immunity." (PMID 23457480, 2013). "However, unexpectedly, the mortality rate of TNF-α KO mice was significantly increased compared with that of WT mice, indicating that TNF-α plays a protective role against fatal infection." (PMID 23940775, 2013). "Therefore, the production of IFNγ, TNFα and IL-17 following immunization coincided with strong protection against infection, potentially due to a synergistic interaction between multiple pro-inflammatory cytokines." (PMID 23613984, 2013). "The reduced growth and inflammation in agsΔ infections was associated with an increase in the expression of the gene coding for the anti-inflammatory IL10 and a decreased expression of the gene coding for the pro-inflammatory TNFα in the lungs." (PMID 24244155, 2013). "Indeed, 100% of TNF-α depleted iNOS−/− mice died within 70 days of infection while only 25% of WT mice died in the same period." (PMID 23936574, 2013). "TNF-α showed a significant increase in both the infected and non-infected neonates when compared to the control neonates indicating that it is increased both in infection and inflammation." (PMID 23869218, 2013). "In the case of infection with Listeria monocytogenes, macrophages and neutrophils were found to be the main source of TNF after bacterial challenge, and this source of TNF was critical to mouse survival, with smaller effects of T cell produced TNF on survival of mice to Listeria challenge." (PMID 23874808, 2013). "These indicate that the control of the immune response of the host to toxins that is mediated by TNFα and IL-16 may represent a potent protective mechanism against infection with invasive microorganisms." (PMID 24116227, 2013). "Our prior studies found that SMARTA effector cells generated following Lm-gp61 infection demonstrated poor function as measured by the frequency of responders able to produce IFNγ, IL-2 and TNFα simultaneously upon restimulation and the amount of cytokine produced on a per cell basis." (PMID 23840678, 2013).